ENSG00000238372
Synonyms: LOC124902079
Gene: Small nucleolar RNA gene on chromosome 8 (101,847,256 to 101,847,360, reverse strand). Ensembl gene ENSG00000238372.
Gene Ontology:
Biological process: RNA processing
Cellular component: nucleolus
Homologues: Paralogues in human: SNORD13 (90% identical), SNORD13P3 (90% identical), SNORD13D (85% identical), SNORD13E (85% identical), SNORD13P1 (85% identical).